MIR4666A (microRNA 4666a)
Synonyms: hsa-mir-4666; MIR4666; hsa-mir-4666a
Gene: MicroRNA gene on chromosome 1 (228,462,074 to 228,462,152, forward strand). Ensembl gene ENSG00000266174.
Homologues: Orthologues: chimpanzee MIR4666A (100% identical).